MIR4770 (microRNA 4770)
Synonyms: hsa-mir-4770
Gene: MicroRNA gene on chromosome X (6,383,906 to 6,383,963, reverse strand). Ensembl gene ENSG00000265284.
Homologues: Orthologues: chimpanzee MIR4770 (100% identical).